IL18 (interleukin 18)
Diseases named in the same sentence as IL18 in open-access papers (continued):
Sharing a sentence is not in itself a finding about the gene and the disease.
cardiac hypertrophy (19 papers, 2013 to 2025). "There are various causes of cardiac hypertrophy, and one of them is IL-18 acting as a cellular prehypertrophic cytokine." (PMID 37551283, 2022). "We have provided evidence that AA development in mice is associated with abnormal heart hypertrophy, associated with elevation of Il18, Col5a1 and cardiac remodelling marker, cTnI." (PMID 23658656, 2013). "This suggests that chronic serum IL-18 elevation is associated with cardiac hypertrophy." (PMID 37551283, 2022). "IL-1-β decreases the expression of SERCA (sarcoplasmic reticulum calcium ATPase), and phospholamban (PLB), which can induce diastolic dysfunction, while IL-18 induces fibrosis and cardiac hypertrophy resulting in diastolic stiffness and concentric remodeling." (PMID 36837434, 2023). "Pyrroloquinoline quinone inhibited ROS and NF-κB activation inhibited NLRP3 inflammasome and Caspase-1, IL-1β and IL-18 expression, and improved myocardial hypertrophy and cardiac fibrosis." (PMID 35509275, 2022). "IL-18, a myocardial pro-inflammatory cytokine, is raised the serum of sick persons with cardiac hypertrophy, and hypertrophy-related genes are down-regulated in IL-18 knockout mice, suggesting a key role in cardiac hypertrophy." (PMID 35647057, 2022). "Many pro-inflammatory factors are involved in pressure overload-induced cardiac hypertrophy in mice, including IL-1β, IL-6, IL-18, and TNF-α." (PMID 34168567, 2021). "Collectively, this study revealed a previously unrecognized involvement of caspase-1 in cardiac HP by regulation of IL-1β and IL-18 and shed light on caspase-1 as an antecedent indicator and target for cardiac hypertrophy." (PMID 33842546, 2021). "Since IL18 induces pathological cardiac remodeling, cardiomyocyte hypertrophy and increased fibronectin expression, high levels of IL18 are expected to lead to cardiac hypertrophy and fibrosis, with a deleterious impact on heart function." (PMID 33193300, 2020). "Overall, the bioinformatics approach using IPA markedly pointed out that IL-18 acts as a critical initiator in the network of cardiac hypertrophy, suggesting the potential involvement of the secreted IL-18 on FC progression." (PMID 27888626, 2016). "Mapping these genes to the network of cardiac hypertrophy revealed the vital role of IL-18 that participate in FC." (PMID 27888626, 2016). "Gene IL23R is weakly associated (p- value 2.19×10−18) with levels of interleukin 18 but also with adiponectin and ECG measures of ventricular hypertrophy)." (PMID 25329069, 2014). "Cas-1 cut leads to the cleavage of downstream cytokines pro-Interleukin-1 beta (pro-IL-1β) and pro-Interleukin-18 (pro-IL-18) into their mature forms IL-1β, IL-18, thereby inducing cardiomyocyte damage and subsequently resulting in myocardial hypertrophy, fibrosis, and impaired cardiac function." (PMID 40242439, 2025). "However, the relationship between IL-18 signaling, cardiac hypertrophy, and the molecular mechanisms involved remain to be fully elucidated." (PMID 37551283, 2022). "The relationship between IL-18 signaling and cardiac hypertrophy remains to be fully elucidated." (PMID 37551283, 2022). "However, like the relationship between IL-18 signaling and cardiac hypertrophy, the role of HTR2B in cardiomyocyte hypertrophy remains to be fully elucidated." (PMID 37551283, 2022). "In addition, circulating IL-18 levels in patients with left ventricular hypertrophy were significantly higher than hypertensive controls with ventricular hypertrophy." (PMID 33924567, 2021). "The beta values for IL-18 and IL-6 were equivalent, whereas considering the critical roles of IL-18 in heart diseases and cardiac hypertrophy, IL-18 may represent a better biomarker that can reflect the development of FC in patients with IVS4+919 G>A mutation." (PMID 27888626, 2016). "Moreover, neutralization of IL-18 has been shown to partially prevent hypoxia-induced cardiac hypertrophy in mice." (PMID 27888626, 2016).
cardiac hypertrophy (continued). "Furthermore, it has been reported that treatment of H9c2 cardiomyocytes with IL-18 activated the PI3K-PDK-Akt/PKB signalling pathways that led to cardiac hypertrophy 50,51." (PMID 25946687, 2015). "Injection of IL-18 into mice induces myocardial hypertrophy and heart remodeling." (PMID 23658656, 2013). "Activation of these pathways by IL-18 signaling may be related to cardiac hypertrophy." (PMID 37551283, 2022). "Therefore, IL-18 is considered to play an important role in maladaptive myocardial hypertrophy." (PMID 37551283, 2022). "Therefore, HTR2B might play an important key role in the process of IL-18-induced myocardial hypertrophy." (PMID 37551283, 2022). "In the present study, we found IL-18 upregulated HTR2B and played a critical role in myocardial hypertrophy." (PMID 37551283, 2022). "Increased IL18 activity in the heart could lead to cardiac hypertrophy and increased cell apoptosis without direct lymphocyte infiltration." (PMID 23658656, 2013).
Cerebral ischemia (19 papers, 2010 to 2025). Restriction of arterial blood supply to the brain associated with insufficient oxygenation to support the metabolic requirements of the tissue. "In the presence of cerebral ischemia, activated cells (including neurons, astrocytes, and endothelial cells) release pro-inflammatory cytokines such as IL-1β, IL-6, and IL-18, which induce the death of neurons and glial cells." (PMID 38601463, 2024). "After the SD rats were modeled by MCAO and orally administered YYTNG, the levels of TNF-α and IL-18 in the plasma of the rats with cerebral ischemia-reperfusion at different time points revealed a downward trend." (PMID 36016577, 2022). "Our results confirmed that the levels of IL-1β and IL-18 were significantly upregulated after cerebral ischemia." (PMID 35690810, 2022). "To determine the effect of QNDP on pro-inflammatory cytokines after cerebral ischemia in rats, we detected the mRNA levels of IL-1β, IL-18 in the ischemic cortex by real time PCR." (PMID 32153398, 2020). "At present, little research on the relationship between IL-18 and cerebral ischemia has been conducted, but it is considered to be a pro-inflammatory cytokine similar in structure to IL-1β." (PMID 32194375, 2020). "Studies have shown that IL-18 mRNA is detected by reverse PCR at 48 h after cerebral ischemia, reaching a peak at 7–14 d." (PMID 32194375, 2020). "To elucidate a functional role of IL-18 in cerebral ischemia we investigated infarct size and functional outcome 24 hours and 48 hours after tMCAO in adult mice with IL-18 deficiency." (PMID 20150990, 2010). "Interleukin-18 (IL-18) is a proinflammatory cytokine of the interleukin-1 family which is upregulated after cerebral ischemia." (PMID 20150990, 2010). "In conclusion, downregulation of PHGDH in astrocytes post cerebral ischemia-reperfusion predominantly drives astrocyte pyroptosis via oxidative stress, resulting in the release of pro-inflammatory cytokines (e.g., IL-1β and IL-18) and subsequent exacerbation of ischemia-reperfusion injury." (PMID 41344159, 2025). "After cerebral ischemia, increased level of IL-18 mRNA has been found in rat brain tissues." (PMID 38421829, 2024). "Interestingly, miR-124 upregulation plays a protective role in cerebral ischemia–reperfusion injury by restricting pyroptosis as evidenced by the limited expressions of IL‐1β, IL‐18, Caspase-1, and GSDMD." (PMID 36243708, 2022). "In our present study, QNDP could reduce the expression of NLRP3, cleaved caspase-1, IL-1β, and IL-18, alleviate brain edema, and improve the neurological function after cerebral ischemia." (PMID 32153398, 2020). "The peak expression of IL-1β mRNA was at 16 h, and it was then downregulated, suggesting that IL-18 may have a certain degree of regulation on the inflammatory response in the late stage of cerebral ischemia." (PMID 32194375, 2020). "Three of them (Ephx2, F2r and Il18) are known as contributing to brain ischemia." (PMID 32039698, 2019). "Differently from TNF-α, IL-18 might act as a delayed mediator of neuroinflammation, in agreement with data obtained in experimental models of brain ischemia and trauma." (PMID 22642744, 2012). "To further investigate whether MFSCE attenuates neuroinflammation after cerebral ischemia, we determined the expression of NLRP inflammasome-associated proteins, including NLRP1, NLRP3, ASC, CL-caspase-1, CL-caspase-11, IL-1β, and IL-18 in the ischemic cortex using Western blotting." (PMID 35454994, 2022). "The functional role of IL-18 in cerebral ischemia is unknown." (PMID 20150990, 2010). "In cerebral ischemia, NLRP3 inflammasome activation evoked the cleavage of caspase-1, thereby cleaving GSDMD, pro-IL-1β, and pro-IL-18 to GSDMD-N, mature IL-1β, and IL-18, respectively." (PMID 34630845, 2021).
Cerebral ischemia (continued). "The studies reported that the activation of the NLRP3 inflammasome leads to the development and release of inflammatory cytokines IL-1β and IL-18, suggesting the role for the NLRP3 inflammasome in the initiation and development of cerebral ischemia." (PMID 32153398, 2020). "The assembly of the inflammasome is also a key part of the pyroptotic pathway during cerebral ischemia, and the upregulation of the NLRP3 inflammasome complex, as well as IL-1β and IL-18, has been demonstrated in the brain tissue of patients with cerebral ischemia." (PMID 37373274, 2023). "Concurrently, the anti-inflammatory property of CEP enables its use in the treatment of cerebral ischemia/reperfusion injury, wherein CEP inhibits NLRP3 signaling, and caspase-1, thereby suppressing the overproduction of IL-1β and IL-18, thus attenuating cerebral ischemia/reperfusion injury." (PMID 36677811, 2023). "After cerebral ischemia, the changes in the intracellular microenvironment trigger the NLRP3 inflammasome (NLRP3/ASC/CASPASE-1) activation, which leads to the secretion of IL-1β and IL-18 and finally mediated cell death." (PMID 36091745, 2022). "Cerebral ischemia/reperfusion injury can activate the NLPR3 inflammasome and promote the secretion of related inflammatory factors such as interleukin-1 (IL-1) and interleukin-18 (IL-18), thus inducing neuronal cell death." (PMID 33820869, 2021). "A1 astrocytes-secreted IL-1β, IL-6, IL-18 and TNF-α aggravate the neuroinflammation and deteriorate the brain tissue damage.Whereas, A2 astrocytes produce brain-derived neurotrophic factor (BDNF), which is known as neurotrophic factor and provide neuroprotection against cerebral ischemia injury." (PMID 38421829, 2024).
myocarditis (19 papers, 2004 to 2026). Myocarditis is a condition that is characterized by inflammation of the heart muscle (myocardium). "Interleukin-18 (IL-18), another inflammasome-related cytokine, has also been associated with myocardial inflammation in both COVID-19 infection and vaccine-related myocarditis." (PMID 41472298, 2025). "Studies have shown myocarditis is associated increase of pro‐inflammatory cytokines IL‐1, and IL‐18." (PMID 39570098, 2024). "In mice, TLR4 deficiency has been shown to decrease levels of IL-1β and IL-18, as well as viral replication and myocarditis." (PMID 37175422, 2023). "During myocarditis, IL-12 signaling increases IL-1β and IL-18, while IL-12 deficiency decreases inflammation and viral replication during myocarditis." (PMID 37175422, 2023). "They found that the severity of myocarditis, degree of viral replication, and levels of IL-1β/IL-18 expression were significantly reduced in TLR4-deficient mice and that TLR4 as well as IL-12Rβ1 aggravated CVB3 infection and myocarditis but IFN-γ inhibited viral replication." (PMID 29854842, 2018). "Additionally, circulating IL-18 or even cardiac troponin combined with IL-1 could improve diagnostic specificity for myocarditis if validated." (PMID 40832143, 2025). "A predominance of Th1-type immune response over Th2-type response was shown in the heart and periphery of male mice with myocarditis, suggesting a contribution of IL-18 and Th1 immune activation to sex-dependent cardiac inflammation." (PMID 35251049, 2022). "IL18 is expressed in myocardium early in the course of experimental myocarditis induced by T. cruzi, leading to production of IFNγ." (PMID 33193300, 2020). "Recently, we demonstrated that CB3 infection increases IL-1β and IL-18 levels in the heart during acute myocarditis through IL-12Rβ1 and TLR4 signaling." (PMID 15550215, 2004). "Furthermore, IL-1β and IL-18 levels are elevated in myocarditis, implicating inflammasome activation; indeed, myocardial biopsies from myocarditis patients have shown increased NLRP3 and IL-1β expression." (PMID 40832143, 2025). "Studies in mouse models of coxsackievirus infection have shown that testosterone promotes TLR4 signalling in myocarditis, which might contribute to increased levels of IL-1β and IL-18, leading to cardiomyocyte apoptosis and contractile dysfunction." (PMID 38681683, 2024). "In addition, it was reported that NLRP3 inflammasome expression, an upstream signal for IL-18 activation, was upregulated in patients with myocarditis or pericarditis." (PMID 35251049, 2022). "Furthermore, the severity of acute myocarditis directly correlates with increased levels of IL-1β and IL-18 in the heart." (PMID 15550215, 2004). "This study obtained left ventricular endomyocardial biopsies from both natural COVID-19 infection and vaccination myocarditis, with IFN-γ being predominant in natural infection, while IL-16 and IL-18 were in vaccination." (PMID 40573879, 2025). "Cardiac IL-18 and IL-1β levels, the outcome of NLRP3 inflammasome activation, in male mice with myocarditis were significantly higher compared with females." (PMID 35251049, 2022). "Although IFNγ is increased in our model of CVB3 myocarditis in males, we showed that elevated IFN levels in male BALB/c mice with myocarditis are mediated by IL-18, which is downstream from TLR4, rather than traditional STAT4/IL-12 transcriptional activity." (PMID 39696682, 2024). "Particularly, male mice with CVB3-induced myocarditis display a higher Th1 response and release of pro-inflammatory cytokines such as IL-1β, IL-18, and IFN-γ, whereas female mice develop predominantly an anti-inflammatory Th2 response in the context of CVB3-induced myocarditis." (PMID 39273613, 2024). "Moreover, the cytokine levels of TNF-α, IL-1β, and IL-18 were significantly reduced in LQF group, suggesting that LQF can alleviate myocardial inflammation induced by MI, thereby improving the cardiac function." (PMID 35310035, 2022).
myocarditis (continued). "TLR4 and IL-12Rβ1 might share common downstream pathways that directly affected IL-1β and IL-18 production, and IL-1beta and IL-18 played an important part in the pathogenesis of CVB3-induced myocarditis." (PMID 29854842, 2018).
hyperuricemia (18 papers, 2012 to 2025). An abnormally high level of uric acid. "For example, previous studies reported that gene polymorphism in Uygur Chinese may be correlated with hyperuricemia such as ApoE E4, IL-8, IL-1RL1, IL-18 and SLC17A1 genes." (PMID 32238146, 2020). "Expression of XOD and proteins associated with NLRP3 inflammasome signaling, such as TLR4, NF-κB, NLRP3 and IL-18, was increased in the liver tissues of mice suffering from hyperuricemia induced by yeast extract compared with those in the normal group." (PMID 37124197, 2023). "The results showed that the expression of the NLRP3 inflammasome in peripheral blood mononuclear cells, and the levels of IL-1β and IL-18 in the plasma were upregulated in the gouty nephropathy group compared with the control and hyperuricemia groups." (PMID 34305953, 2021). "The results showed that compared to those in the healthy control group, the serum inflammatory cytokine levels of IL‐1β and IL‐18 in hyperuricaemia patients were significantly higher." (PMID 34296520, 2021). "It was found that IL-1β and IL-18, two inflammatory cytokines, was up-regulated in subtotal nephrectomy or hyperuricemia-induced renal tubular injury." (PMID 30807290, 2019). "Hyperuricemia is accompanied by inflammatory markers, including IL-6, IL-18, hs-CRP, and TNF-α." (PMID 35453642, 2022). "Moreover, IL-18 level in the cardiac of hyperuricemia mice was also elevated." (PMID 36986461, 2023). "Expression of NLRP3 and ASC-speck protein was significantly increased in PPMS, SMS, and AMS patients, but IL-18 and caspase-8 production was significantly increased only in PPMS, in whom a direct correlation between hyperuricemia and caspase-8 was detected." (PMID 29780394, 2018). "Hyperuricemia amplifies these processes: xanthine oxidase-derived reactive oxygen species, reduced nitric-oxide bioavailability, and, to a larger extent, NLRP3 inflammasome activation (IL-1β/IL-18) allow for near-constant “inflammatory priming”." (PMID 41515581, 2025).
multiple myeloma (18 papers, 2017 to 2024). "Elevated BM IL-18 levels are also associated with poor overall survival of multiple myeloma patients." (PMID 34084749, 2021). "In multiple myeloma, the increase in serum IL-18 is associated with disease progression and lower chances of patient survival." (PMID 33972620, 2021). "Remarkably, while reduced myeloma cell proliferation was displayed after IL-12 and IL-18 administration in Rag-deficient animals, this was overturned when animals were treated with IL-33 together with IL-12 and IL-18." (PMID 35740879, 2022). "Furthermore, IL-18 is also involved in the disease progression and immunosuppression of multiple myeloma (MM), and a high level of IL-18 is associated with a poor prognosis in such patients." (PMID 34805183, 2021). "It has also been recently shown that IL-18 administration after bone marrow transplantation induced the cytotoxicity of T cells in a mouse model of myeloma and enhanced their lethality in a leukemia model." (PMID 37298187, 2023). "In multiple myeloma, the pro-tumoral effect of IL-18 was shown to be due of its release in a NLRP3-dependent from TAMs and favored the immunosuppressive activity of MDSCs." (PMID 37298187, 2023). "The pro-inflammatory cytokine IL-18 modulates the immune microenvironment in multiple myeloma and suppresses the action of T cells." (PMID 37047826, 2023). "This was attributable to IL-18-dependent generation of myeloid-derived suppressor cells (MDSCs), an important driver of the dysfunctional immune environment in human myeloma." (PMID 34149703, 2021). "Vκ*MYC also provided definitive genetic evidence on the involvement of the pro-inflammatory cytokine IL-18 in myeloma progression." (PMID 34149703, 2021). "In this context, one preclinical study on multiple myeloma demonstrated that the inflammasome-derived IL-18 critically contributes to disease progression driving the generation of myeloid-derived suppressor cells (MDSCs)." (PMID 30641867, 2019). "The genetic polymorphisms of CARD8-C10X (rs2043211), NF-κB-94 ins/del ATTG (rs28362491), and IL-18 (rs1946518) contribute to the clinical manifestations of multiple myeloma." (PMID 30211233, 2018). "Using myeloma and osteosarcoma cell lines as targets, we demonstrated here that the treatment of ex vivo-expanded Vγ9Vδ2 T cells with IL-12 and IL-18 enhanced their cytotoxic activity against tumor cell lines." (PMID 28521284, 2017). "It has also been reported that the microenvironment of multiple myeloma is regulated by IL-18." (PMID 37047826, 2023). "Furthermore, NK cells expanded and activated by K562-OX40L-mb-IL-18/IL-21 feeder cells have shown cytotoxic activity against multiple myeloma in in vitro and xenograft mouse models." (PMID 36703992, 2022).